IL1B (interleukin 1 beta)
Diseases named in the same sentence as IL1B in open-access papers (continued):
Sharing a sentence is not in itself a finding about the gene and the disease.
COVID-19 (continued). "Similar to COVID-19-associated myocarditis, autoimmunity-associated myocarditis results in upregulated activation of the NLRP3 and NF-κB pathways in addition to an increase in IL-1β level." (PMID 38650023, 2024). "However, the excessive or dysfunctional release of IL-18 and IL-1β leads to excessive inflammation, exacerbates tissue damage, and leads to cytokine storms observed in severe COVID-19 cases." (PMID 38399989, 2024). "Furthermore, according to a previous report, COVID-19 can activate NETs, which then activate IL-1-β, and IL-1-β to form an IL-1β-NET loop." (PMID 38882332, 2024). "Interestingly, the genetic variant chrX:15,584,534_ of the ACE2 gene correlated positively with CD40L, IL-1β, IL-2, IL-15, and IL-17A in COVID-19 patients." (PMID 38855114, 2024). "Moreover, they revealed an “IFN-I-potentiated TNF/IL-1β inflammatory response” in severe/fatal COVID-19 using scRNA-seq analysis, which further clarified the pro-inflammatory role of IFN-I." (PMID 39148728, 2024). "Overall, these findings underscore the potential of CD1C and IL1B as biomarkers for predicting the onset and progression of COVID-19, which could inform therapeutic strategies." (PMID 39622956, 2024). "The presence of CD1C (IVW OR = 0.804, 95% CI: 0.658 − 0.984, p = 0.034), IL1B (IVW OR = 0.846; 95% CI: 0.732–0.978; p = 0.024), and SLPI (IVW OR = 0.862; 95% CI: 0.751–0.990; p = 0.035) may be associated with a lower risk of COVID-19." (PMID 39622956, 2024). "Notably, exposure of ECs to COVID-19 plasma characterized by elevated proinflammatory cytokine levels (specifically, IL-1β, IL-6, and TNF-α) precipitated a redox-sensitive upregulation of SGLT-2 expression." (PMID 38448675, 2024). "Several studies have shown a significant association between high levels of Gal3 in the blood serum and COVID-19 severity, along with increased pro-inflammatory cytokines (IL-1β, TNF-α, and IL-12), chemokine C-C, and chemokine receptor type 5 (CCR5) expression in T cells." (PMID 39125989, 2024). "Additionally, there was increased secretion of several EC-derived inflammatory molecules previously identified in COVID-19 patients, including IL-1β, IL-6, and sICAM-1." (PMID 38576426, 2024). "Indeed, NLRP3 inflammasome activation, which induces IL-1β, has been described in neutrophils from severe COVID-19 patients and this pathway seems to be particularly involved in older patients." (PMID 38715114, 2024). "Early (0–4 week) IL-1β and BMI at COVID-19 onset were predictive of PASC at 24 weeks." (PMID 39008486, 2024). "Treatment of these mice with anakinra (which blocks both IL-1α and IL-1β signaling) or with antibodies selectively targeting IL-1α significantly attenuated COVID-19-like pulmonary immunopathology, potentially identifying IL-1α as a mediator of inflammation and tissue-specific injury." (PMID 39882243, 2024). "It has been shown that empty LNPs made by MC3 lipids could not stimulate IL-1β production, while LNPs made by SM-102 (used in the COVID-19 vaccine designed by Moderna) were potent inducers of IL-1β." (PMID 39066318, 2024). "Out of the 17 cytokines tested, nine (IL-1β, IL-2, IL-4, IL-5, IL-12, IL-13, IL-17, granulocyte colony-stimulating factor (G-CSF), granulocyte-macrophage colony-stimulating factor (GM-CSF)) were undetectable in the peripheral blood of COVID-19 patients." (PMID 39408857, 2024). "In this line, a recent study unveiled a spontaneous NLRP3 inflammasome over-activation and IL-1β secretion in monocytes from severe COVID-19 patients that could be reverted by treating the patients with the IL-1 receptors blocker anakinra." (PMID 38225643, 2024). "Except for IL-8 decreased in the second trimester after infected with SARS-CoV-2, IL-2, TNF-α, TNF-β, IFN-γ, IL-4, IL-5, IL-6, IL-10, IL-17A, IL-17F, IL-22, IL-1β and IL-12p70 didn't change in the three trimesters between healthy pregnancies and pregnant women with COVID-19." (PMID 39113896, 2024).
COVID-19 (continued). "Moreover, NLRP3 inflammasome products, such as IL-1β and IL-18, are increased in patients with severe acute COVID-19 and positively correlated with adverse clinical outcomes." (PMID 39012668, 2024). "Interestingly, several cytokines such as IFN-γ, IFN-α, IL-1β, IL-2, IL-12p70, IL-17A and IL-33) decreased in moderate and severe COVID-19 patients compared to mild cases or healthy controls." (PMID 38855114, 2024). "Also, elevated levels of NLRP3 inflammasome activation that serves as a platform for mature IL-1β release is directly related to hyperinflammation as well as increased disease severity of COVID-19 patients." (PMID 37799713, 2023). "The breakdown of the BBB triggers a severe inflammatory response, causing the cytokine storm (release of IL-1β, IL-6, TNF-α, etc.)characteristic of the severe phase of COVID-19, which includes the recruitment of macrophages and lymphocytes and the activation of astrocytes and microglia." (PMID 36998270, 2023). "When compared to non-infected controls, protein levels of caspase-1, ASC, IL-1β and IL-18 were higher in patients with active (Positive) COVID-19 (median day of blood collection: 11 days) and in patients who recently recovered from COVID-19 (median day of blood collection: 61.5 days)." (PMID 37168848, 2023). "Lactiplantibacillus plantarum is a probiotic that was reported to modulate cytokine production by increasing TNF-α, IL-1β, IL-18, and IL-8, and reducing IL-6, a critical factor in immune dysregulation in COVID-19, thus enhancing the activity of natural killer cells." (PMID 37298539, 2023). "All genes excepting IL1B (p=0.878) showed a significantly higher expression (p<0.005) in COVID-19 cases than in the samples from the control group suggesting that in asymptomatic-mild cases antiviral and immune system cells recruitment gene expression is being promoted." (PMID 37389217, 2023). "However, as with IL-6, results from trials of IL-1β blockade (eg, anakinra, canakinumab) in COVID-19 were also conflicting, potentially due to the timing of initiation and extent of inflammatory disease." (PMID 37427016, 2023). "Finally, interleukin-18 is a highly predictive biomarker of death by COVID-19, and measurements in bronchoalveolar lavage fluid (BALF) showed a significant increase in the interleukin-1β (IL-1β) level in patients with moderate to severe COVID-19." (PMID 37476705, 2023). "We believe the preponderance of evidence suggests IL-1β is not a cause of organ malfunction or death in COVID-19." (PMID 37928695, 2023). "Direct inflammasome inhibition attenuated COVID-19 severity in a preclinical model, but potent forms of such inhibitors are not yet in clinical use, which leaves the option of inhibiting downstream cytokines IL-1β and IL-18." (PMID 37582864, 2023). "Intriguingly, inflammasome activation was primed and the formation of IL-1β was robustly increased in macrophages from convalescent COVID-19 patients upon S protein stimulation, suggesting SARS-CoV-2-specific innate immune memory following recovery, which declined over time." (PMID 37251383, 2023). "Probiotics also have an immunomodulating role in the cytokine storm (IL-1B, IL-6, IL-15, IL-15, IL-17 IFN-g, TNF-a), and it can thus be deduced that probiotics are involved in fighting the cytokine storm associated with COVID-19." (PMID 37049576, 2023). "Colchicine may also be appropriate in the treatment of COVID-19, as it can inhibit neutrophils, IL-1β and the inflammation/thrombosis interface." (PMID 37228604, 2023). "Type I IFN responses occurred simultaneously with inflammatory responses driven by TNFα and IL-1β in classical monocytes from patients with severe COVID-19, suggesting that type I IFNs may play an important role in exacerbation." (PMID 37108051, 2023). "Notably, among cytokines, IL-6, TNF-α and IL-1β have been identified as the key targets of COVID-19-induced PF." (PMID 37601070, 2023).
COVID-19 (continued). "Moreover, we proposed BAL IL-1β as a promising tool for supporting VAP diagnosis in COVID-19 patients." (PMID 37749631, 2023). "In this study blood levels of sP2X7R measured at the time of diagnosis at hospital admission in a cohort of COVID-19 patients were correlated to (a) several markers of inflammation and tissue damage, (b) sNLRP3, IL-6, IL-10, and IL-1β levels, and most importantly, (c) disease progression." (PMID 37215142, 2023). "Moreover, IFN-I response co-existed with the TNF-alpha/IL-1β-driven inflammation was observed in patients with severe COVID-19." (PMID 37753372, 2023). "Release of inflammasome products, such as IL1B and cytokine storms are hallmarks of COVID-19 infection and smoking may critically exacerbate COVID-19-related inflammation." (PMID 37147350, 2023). "Measurement of miRNA-16–2-3P, miRNA-618, IL-1β could be a good predictor of COVID-19 patient outcome." (PMID 37222789, 2023). "Furthermore, in the comparison of mass cytometry analysis of COVID-19 and control lung monocytes and macrophages, higher concentrations of IL-1β (a profibrotic factor) were observed in COVID-19 samples." (PMID 37601070, 2023). "Moreover, in contrast to what has been described, levels of TNF and IL-1β are found to be significantly reduced in our whole cohort of COVID-19 patients." (PMID 36861136, 2023). "Our findings may support the evidence that the NLRP3 inflammasome plays a crucial role in the innate immune response to SARS-CoV-2 virus infection due to the increased tissue expression of IL-1β in the COVID-19 group compared to the CONTROL and H1N1 groups." (PMID 36992415, 2023). "This hypothesis is based on IL-1β’s established role in other inflammatory responses unrelated to COVID-19 and its central role in regulating immune responses." (PMID 38090572, 2023). "= −1.08, p = 0.04) in the serum level of interleukin-1 beta in COVID-19 patients." (PMID 36837428, 2023). "Several studies investigating BALF IL-1β levels in patients with COVID-19 have been reported." (PMID 37928695, 2023). "The consumption of omega-3 fatty acids has been shown to lower markers of inflammation in serum, such as C-reactive protein, interleukin-6 (IL-6), interleukin-1β (IL-1β), and tumor necrosis factor-α (TNF-α), and other inflammatory factors that have been implicated in the cytokine storm of COVID-19." (PMID 37515117, 2023). "In line with our findings, several reports described the overproduction of IL-6, TNF-α, and IL-1β, leukopenia and coagulopathy, marked by platelet activation and high D-dimer levels, accounting for the development of the more severe forms of the COVID-19." (PMID 37283924, 2023). "NLRP1 and ASC may have a more critical role in the generation of the active form of IL-1β in COVID-19 patients compared to NLRP3." (PMID 37723427, 2023). "In the present research, we first observed, in line with the literature, that the SARS-CoV-2 S1 spike surface protein is sufficient alone to activate the production of key COVID-19 pro-inflammatory cytokines (IL-1β, IL-6, and IL-8) in alveolar A549 cells, a major COVID-19 cell-type target." (PMID 37834316, 2023). "In general, infection, which in the case of COVID-19 may be prevented by vaccination, may be connected with elevated levels of cytokines in the amniotic fluid: interleukin-1β (IL-1β), interleukin-6 (IL-6), and prostaglandins, such as PGE2 and PGE2a." (PMID 37629228, 2023). "Activation of the NLRP3 inflammasome, which results in the production of active IL-1β, occurs during the early stages of RNA virus infection; it can also be induced by peripheral blood mononuclear cells from patients with moderate or severe COVID-19." (PMID 37515185, 2023). "Interestingly, only inflammatory IL-1β (P = 0.008) and IL-6 (P<0.05) showed significantly increased levels in long-COVID-19 compared to unexposed healthy individuals." (PMID 37018291, 2023).
COVID-19 (continued). "Second, some inflammatory markers associated with critical cases of COVID-19, such as IL-6, interleukin (IL)-1β, and TNF-α, were not included." (PMID 36999038, 2023). "We analyzed the protein levels of the inflammasome signaling proteins caspase-1, ASC, IL-1β and IL-18 in patients with COVID-19 and patients who had recently recovered from a COVID-19 infection and compared them to the levels in plasma samples from healthy donors, who never had COVID-19." (PMID 37168848, 2023). "Among non-COVID-19 patients, IL-1β has been proposed as promising markers for VAP." (PMID 37749631, 2023). "From our study we suggest that measurement of the IL-1β, IL-8, and host miRNA response could improve COVID-19 detection, outcome prediction and this potentially useful tool for early management of patients with severe forms." (PMID 37222789, 2023). "Furthermore, the higher levels of IL-1β, IL6, IL-12p70, IL-17A, TNF-α, and IFN-γ are consistent with the inflammatory profile of COVID-19-associated lung injury." (PMID 38067158, 2023). "An enlarged subgroup of CD14+IL-1β+ monocytes can elevate IL-1β in COVID-19 patients." (PMID 37051070, 2023). "Patients in stage IV of COVID-19 had significantly higher serum level of pro-inflammatory cytokines IL-1β (p = 0.001), TNF-α (p = 0.012) and IL-12 (p = 0.001) as well as immunosuppressive IL-10 (p = 0.001) compared to the patients in less severe stages of disease." (PMID 36702907, 2023). "In the pre-COVID-19 data set, IL1β, IL6, and TNF were found to have decreased in both groups." (PMID 37546047, 2023). "It seems IL-1α is studied less frequently in COVID-19 than IL-1β." (PMID 37928695, 2023). "A review study observed that variants in cytokine genes such as IL-1β, IL1R1, IL1RN, IL-6, IL-17A, FCGR2A, and TNF may be associated with disease susceptibility and/or severity, cytokine storm, and/or COVID-19 complications like thrombosis." (PMID 37662953, 2023). "Moreover, IL-1β is also associated with COVID-19 pathogenesis, and the NOD-like receptor family pyrin domain-containing 3 (NLRP3) inflammasome, which promotes the production of active IL-1β, is activated in COVID-19 patients." (PMID 37515185, 2023). "However, even 2–3 months after recovering from COVID-19, alterations in the levels of both pro-inflammatory cytokines, such as IL-1β, IL-6, TNFα, and the anti-inflammatory cytokine IL-10, have been observed in semen." (PMID 37958725, 2023). "Interestingly, following LPS and BzATP stimulation, we observed that PBMCs of COVID-19 patients significantly release more IL-1β and IL-6 compared to the control group." (PMID 37986089, 2023). "Studies of COVID-19 patients also showed significant increases in proinflammatory cytokines and chemokines, including IL-6, IL-1β, TNF-α, and granulocyte–macrophage colony-stimulating factor, in patients’ plasma, with much higher levels in the plasma of critically ill patients." (PMID 37628764, 2023). "The weighted average of median blood IL-1β in COVID-19 is 0.88 pg./mL." (PMID 37928695, 2023). "According to recent studies, the secretion of cytokines, such as interleukin (IL)-1β, IL6, and IL-10, and mediators such as TNF-α have been significantly stimulated in patients with COVID-19 and are associated with rapid disease progression in high-risk patients." (PMID 37047078, 2023). "The elevation of certain cytokines in COVID-19 patients (i.e., IL-6, IL-1β, and IFN-γ), may also be due to the presence of the virus or its remnants in PASC patients." (PMID 36947108, 2023). "We compared IL1B+ COVID-19 infected BALF (27.7%) and IL1B+ healthy control BALF." (PMID 37737611, 2023). "In addition, other studies reported that IL-1β was also increased in COVID-19 patients and in particular in severe cases." (PMID 36861136, 2023).
COVID-19 (continued). "In particular, PC1 reflected the known hyper-inflammatory phenotype of COVID-19 (with greatest contributions from IL-2, IL-6, IP-10, TNF-α, IL-10, IL-33 and IL-1β) which was independently associated with severe disease, requirement for invasive mechanical ventilation and mortality." (PMID 37063871, 2023). "Notably, the correlations of T helper naïve and effector memory cells, T helper 1–17 cells, TNF, IL-10, IL-1β, IL-8, among others, showed differences between healthy controls and COVID-19 patients." (PMID 36861136, 2023). "Different researchers have reported that COVID-19 patients show increased levels of pro-inflammatory cytokines, such as IL-6 and IL-1β, indicating that their modulation might affect patients’ outcomes." (PMID 37986089, 2023). "The regulation of inflammatory mediators, such as TNF-α, IL-6, IL-1β, and leukotriene B4, could play a crucial role in suppressing inflammatory diseases such as COVID-19." (PMID 36611603, 2023). "Although not statically significant, the polar charts show a signal towards the reduction in the production of pro-inflammatory cytokines, and specifically IL-1β, IL-2, IL-12, IL-13, IL-17A secreted by M2 macrophages of COVID-19 patients, after PD1 stimulation." (PMID 37153620, 2023). "However, the 3 studies describing most COVID-19 patients referenced above measured IL-1β in 2,001 patients and in healthy controls." (PMID 37928695, 2023). "Moreover, one study showed a positive correlation between gal-1; levels of pro-inflammatory cytokines such as Interleukin-1 beta (IL-1β), IL-6, and IL-23; and COVID-19 severity, suggesting that gal-1 acts as an alarmin." (PMID 37475853, 2023). "Elevated IL-1β levels are found in patients with severe COVID-19, indicating its excessive production may worsen the disease." (PMID 37446547, 2023). "Thus, COVID-19 exosomes appeared to trigger IL-1β production through activation of the NLRP3 inflammasome in both of the endothelial cells." (PMID 35587188, 2022). "Elevated IL-1β activity is a feature of COVID-19 and periodontitis." (PMID 36366382, 2022). "In severe COVID-19 cases, the production of pro-inflammatory cytokines, including IL-1β, IL-6 and TNF-α, is increased leading to the generation of cytokine storm, inducing futher unfovarable outcome and may eventually lead to lymphopenia." (PMID 35911748, 2022). "However, other authors showed that recombinant SARS-CoV-2 S protein increased NLRP3 protein expression and induction of IL-1β in macrophages from patients with COVID-19 through the up-stream activation of TLR2." (PMID 36498845, 2022). "The S1 spike protein stimulated the production of cytokines: in human lung A549+ cells, we found that S1 spike stimulated the production of the key COVID-19 cytokine IL-1β, and in human intestinal epithelial Caco-2 cells, S1 stimulated the production of IL-6 and IL-8 cytokines." (PMID 36296272, 2022). "Severe COVID-19 patients developed much higher serum concentrations of pro-inflammatory cytokines and chemokines (e.g., IL-1β, IFN-α, IL-1RA, and IL-8) than those with milder disease, indicating that the cytokine dysregulation was closely correlated with disease severity." (PMID 35534483, 2022). "Furthermore, AMP5A suppresses a distinct set of pro-inflammatory cytokines (including IL-1β, IL-6, IL-12, and CXCL10) associated with COVID-19 and pro-inflammatory NF-κB activation." (PMID 35261923, 2022). "There were significant association between IL-1β & neutrophils (r = 0.42, p<0.05), IL-10 & WBC (r = 0.39, p<0.05), IL-10 & Basophils (r = -0.51, p<0.01), IL-17 & Neutrophil (r = 0.39, p<0.05) in the active COVID-19 cases." (PMID 36094915, 2022). "The expression of inflammasome components (cleaved IL-1β, cleaved-CASP1, ASC, and NLRP3) was increased in COVID-19 variants and overexpressed in COVID-19/B.1.1.7 patients (p < 0.05 compared with COVID-19/B.1 variant) as indicates the immunohistochemical composite score." (PMID 36498845, 2022).